CTH (cystathionine gamma-lyase)
Diseases named in the same sentence as CTH in open-access papers (continued):
Sharing a sentence is not in itself a finding about the gene and the disease.
mastitis (2 papers, 2022). Inflammation of breast tissue during lactation or postpartum due to an obstructed duct or infection. "Our previous study found that Cystathionine-γ-lyase (CTH) and H2S are correlated with the occurrence and development of Clinical Mastitis (CM) in Holstein cows." (PMID 36233122, 2022). "This suggests that CTH may play an important regulatory role in cow mastitis." (PMID 35681915, 2022).
neuroblastoma (2 papers, 2018 to 2022). Neuroblastoma (NB) is the most common solid, extracranial childhood tumor. "Likewise, CTH inhibition exerted more ferroptosis‐sensitizing effects on MYCN‐high adrenergic neuroblastoma cells than on MYCN‐high mesenchymal neuroblastoma cells." (PMID 35908258, 2022).
ovarian carcinoma (2 papers, 2016 to 2023). A malignant neoplasm originating from the surface ovarian epithelium. "When evaluated in comparison with the large bodies of gene expression data for ovarian carcinoma, robust extraction of reliable protein features with potential clinical relevance, such as CTH, is achieved." (PMID 27713570, 2016). "While we have observed high CTH expression in CCC carcinomas in a large TMA cohort our observations will need to be validated in large independent cohorts of ovarian carcinomas." (PMID 27713570, 2016). "In ovarian cancer cell lines, depletion of the enzyme that catalyzes the metabolic step prior to CTH, cystathionine beta synthase (CBS), induces reactive oxygen species (ROS) accumulation leading to reduced mitochondrial respiration and ATP synthesis." (PMID 27713570, 2016). "Furthermore, in an IHC analysis of a TMA of 485 ovarian cancer samples 75% of CCC cases stained intensely for CTH in contrast to ENOC (17%) and HGSC (2%)." (PMID 27713570, 2016). "In a western blot analysis of a panel of ovarian cancer cell lines of validated histotype; the majority of CCC cell lines showed high expression of CTH and LEFTY1." (PMID 27713570, 2016). "Besides known biomarkers of histotypes, cystathionine∼ gamma-lyase (CTH), a candidate protein biomarker highly expressed in clear cell EOC, was validated in cell lines using Western blotting and in three histotypes of ovarian cancer using immunohistochemistry." (PMID 37209814, 2023).
Acute hepatitis (1 paper, 2020). Acute hepatic injury resulting from inflammation typically accompanied by increased serum alanine transaminase activity. "CTH and CBS are also members of the transsulfuration pathway that metabolizes methionine, and homozygous (CTH−/−) knockout mice displayed acute hepatitis in cases of excessive methionine intake." (PMID 32701483, 2020).
acute lymphoblastic leukemia (1 paper, 2024). Leukemia with an acute onset, characterized by the presence of lymphoblasts in the bone marrow and the peripheral blood. "Peripheral blood mononuclear cells of patients with Acute Lymphoblastic Leukemia exhibited higher cystathionine gamma-lyase protein levels and an elevated level of H2S, which was subsequently reduced by chemotherapy." (PMID 39062461, 2024). "Similarly, MPST (p < 0.001, Log2FC = −1.098) and CBS (p < 0.001, Log2FC = −0.582) also exhibit higher expression levels in Acute Lymphoblastic Leukemia, whereas CTH expression is lower (p < 0.001, Log2FC = 0.644)." (PMID 39062461, 2024).
age-related macular degeneration (1 paper, 2017). Age-related loss of vision in the central portion of the retina (macula), secondary to retinal degeneration. "Decreased CTh might predispose patients with CAD to high-risk phenotypes of age-related macular degeneration such as reticular pseudodrusen and could serve as a potential biomarker of disease in CAD." (PMID 28632734, 2017).
aortic aneurysmal diseases (1 paper, 2025). "The SENP3/CTH axis is therefore an important therapeutic target for aortic aneurysmal diseases." (PMID 40019399, 2025). "A better understanding of the role of SENP3 and CTH in AAA may ultimately lead to new approaches to prevent and treat aortic aneurysmal diseases." (PMID 40019399, 2025).
basal cell carcinoma (1 paper, 2020). A carcinoma involving the basal cells. "InnateDB pathway analyses of genes mapped to independent lead SNPs by FUMA showed a significant overlap between CTh and CSA genes and the Wnt signaling pathway as well as a significant overlap between CV genes and the basal cell carcinoma pathway." (PMID 32963231, 2020).
Cerebral ischemia (1 paper, 2016). Restriction of arterial blood supply to the brain associated with insufficient oxygenation to support the metabolic requirements of the tissue. "With the docking design to galangin, the six proteins (GLUD1, GLUL, GLS, CTH, GOT2 and HP) with high affinity might become its targets for cerebral ischemia." (PMID 27058522, 2016).
cholangiocarcinoma (1 paper, 2021). A carcinoma that arises from the intrahepatic biliary tree (intrahepatic cholangiocarcinoma) or from the junction, or adjacent to the junction, of the right and left hepatic ducts (hilar cholangiocarcinoma). "Furthermore, based on TCGA data, the mRNA expression of CTH decreased in cholangiocarcinoma (CHOL), kidney renal clear cell carcinoma (KIRC) and thyroid carcinoma (THCA) tissues." (PMID 33522955, 2021).
cognitive decline (1 paper, 2019). "Adequate supply of B-vitamins in the elderly, particularly in subjects with MTHFR and CTH gene mutations, appears to be critical to prevent the development of cognitive decline and to halt the progression of LOAD." (PMID 30646578, 2019).
contact dermatitis (1 paper, 2023). An inflammatory skin condition caused by direct contact between the skin and either an irritating substance or an allergen. "However, at the delayed phase (24 h), CTH mRNA was upregulated in the TNCB-treated ears of WT and Mpst–/– mice, whereas MPST mRNA was downregulated in the TNCB-treated ears of WT and Cth–/– mice, suggesting protective roles of CTH against the delayed phase of TNCB-induced contact dermatitis." (PMID 36768979, 2023). "In conclusion, we have found that CTH plays important roles in protecting against contact dermatitis, induced by the specific model hapten (TNCB but not oxazolone)." (PMID 36768979, 2023).
COVID-19 (1 paper, 2025). A disease caused by infection with severe acute respiratory syndrome coronavirus 2. "Virus replication is associated with down-regulation of the H2S-producing enzymes cystathionine-β-synthase (CBS), cystathionine-γ-lyase (CTH), and 3-mercaptopyruvate sulfurtransferase (3-MST) in multiple cell lines and nasopharyngeal swabs of symptomatic COVID-19 patients." (PMID 40388397, 2025).
diabetic foot ulcers (1 paper, 2023). "Specifically, monocytes/macrophages increased expression of several apoptosis genes (including BCL2, FGFR3, FGFR1, CTH, CASP3, IL19, NME5, and S100A8/9) in diabetic foot ulcers compared to monocytes/macrophages in non-diabetic wounds." (PMID 38127424, 2023).
emphysema (1 paper, 2020). "In this research, we found that CTH, the main enzyme products H2S in lung tissues, was impaired in PM-induced mice emphysema and airway inflammation model, which was consistent with our previous study reported that the protein level of CTH was impaired in smokers and COPD patients." (PMID 32116706, 2020).
gastritis (1 paper, 2024). Inflammation of the stomach. "We previously reported that CTH is induced in gastric macrophages from patients with gastric inflammation and cancer, as well as mice with H. pylori-mediated gastritis." (PMID 39427081, 2024). "We reported that CTH supports gastritis induced by the pathogen Helicobacter pylori." (PMID 39427081, 2024).
heart failure (1 paper, 2023). Inability of the heart to pump blood at an adequate rate to meet tissue metabolic requirements. "In the heart CTH is cardioprotective; CTH knockout mice exhibited greater infarct sizes after ischemia-reperfusion and a worse phenotype in animal models of heart failure." (PMID 36860295, 2023).
Hepatitis (1 paper, 2022). Inflammation of the liver. "We previously reported that the 6×Met diet for a week induced acute lethal hepatitis in mice lacking CTH (Cth−/−), demonstrating that transsulfuration played a critical role in the detoxification of excessive dietary Met." (PMID 35055113, 2022).
Hyperglycemia (1 paper, 2020). An increased concentration of glucose in the blood. "Hyperglycemia has been consistently demonstrated to suppress the CTH-H2S pathway in various adipose tissue depots." (PMID 32585916, 2020).
inflammatory bowel disease (1 paper, 2024). A spectrum of small and large bowel inflammatory diseases of unknown etiology. "In conclusion, our data suggest that the enzyme CTH represents a target for clinical intervention in patients with inflammatory bowel disease, potentially by beneficially reshaping the composition of the gut microbiota." (PMID 39427081, 2024).
Insulin resistance (1 paper, 2021). Increased resistance towards insulin, that is, diminished effectiveness of insulin in reducing blood glucose levels. "In the adipose tissue of fructose induced-diabetic rats, the CTH/H2S system was upregulated and negatively associated with glucose uptake in AT, suggesting a pathological role of H2S in insulin resistance." (PMID 33919190, 2021). "Chemical inhibition of CTH with PPG and β-cyano-L-alanine attenuated TNF-α-induced insulin resistance in 3T3-L1 adipocytes." (PMID 33919190, 2021).
insulinoma (1 paper, 2021). "INS-1E rat insulinoma cells expressed CTH, and DL-proparglycine mostly depleted H2S synthesis, indicating that CTH was the principal enzyme for H2S in INS-1E cells." (PMID 33919190, 2021).
non-Hodgkin lymphoma (1 paper, 2023). Distinct from Hodgkin lymphoma both morphologically and biologically, non-Hodgkin lymphoma (NHL) is characterized by the absence of Reed-Sternberg cells, can occur at any age, and usually presents as a localized or generalized lymphadenopathy associated with fever and weight loss. "ADH1B, CTH, and PLOD2 showed overexpression in the lymph node tissue of non-Hodgkin lymphoma patients compared to normal lymph node tissue." (PMID 36755971, 2023).
Obesity (1 paper, 2025). Accumulation of substantial excess body fat. "Analysis of amino acids in urine through metabolomics showed a strong association between childhood obesity and increased levels of AAA, CTH, SER, and aromatic amino acids, particularly TYR, which appears to be a good candidate for obesity biomarkers." (PMID 40365082, 2025).
osteoarthritis (1 paper, 2024). A noninflammatory degenerative joint disease occurring chiefly in older persons, characterized by degeneration of the articular cartilage, hypertrophy of bone at the margins and changes in the synovial membrane. "Moreover, curcumin may have therapeutic effects on osteoarthritis by interacting with the CTH, CBS, CDO1, and PSAT1 proteins involved in cysteine and methionine metabolism." (PMID 37938371, 2024). "For instance, curcumin may exhibit therapeutic effects on osteoarthritis by modulating the CBS, CTH, PSAT1, MAOA, and AOC2 proteins involved in the metabolism of glycine, serine, and threonine." (PMID 37938371, 2024).
pancreatic cancer (1 paper, 2016). "In summary, we revealed the importance of PTGR2/15-keto-PGE2 in antioxidative signaling and in tumor cell death involving xCT and CTH in some of the pancreatic cancer cells." (PMID 26820738, 2016). "These suggest that the role of 15-keto-PGE2 specifically in the regulation of antioxidative signaling through xCT and CTH may not require PPARγ in pancreatic cancer cells." (PMID 26820738, 2016).
sarcopenia (1 paper, 2025). Progressive decline in muscle mass due to aging which results in decreased functional capacity of muscles. "In sarcopenia, CTH is negatively correlated with eosinophils." (PMID 41325398, 2025). "Identifying these 13 ERSRCGs including FOXO1, KAT2A, and CTH brings attention to the central contribution of ER stress in the development of IPF and sarcopenia." (PMID 41325398, 2025). "LASSO regression identified CTH and IDI1 for IPF, and FOXO1, CTH, HSD11B1, GSTK1, and SPTSSA for sarcopenia." (PMID 41325398, 2025). "The findings demonstrated that FOXO1, CTH, HSD11B1, GSTK1, and SPTSSA were the five sarcopenia model genes (SMGs) that were included in the LASSO regression model." (PMID 41325398, 2025). "In general, the validity of the diagnostic models was evident with the values of the predictive models of IPF; CTH, and IDI1 as well as the models of sarcopenia; FOFOXO1, CTH, HSD11B, GSTK1, and SPTSSA." (PMID 41325398, 2025).
schizophrenia (1 paper, 2022). A major psychotic disorder characterized by abnormalities in the perception or expression of reality. "In a predominantly neuronal/endothelial subtype (22% of patients), CTh deviations covaried with polygenic risk for schizophrenia (sczPRS) calculated specifically from genes marking neuronal and endothelial cells (r = −0.40, p = 0.010)." (PMID 35145230, 2022). "For example, CTh alterations characteristic of Subtype I may underlie alterations in neuronal morphology (e.g., reduced neuropil) or cell density (e.g., reduced excitatory pyramidal or GABAergic interneuron populations) observed in neuropathological studies of schizophrenia-affected brains." (PMID 35145230, 2022). "Differences from the null distribution were characterized by stronger negative correlations, meaning that CTh losses covaried with higher cell-type gene expression in schizophrenia." (PMID 35145230, 2022).
sulfite oxidase deficiency (1 paper, 2023). "Further, it was shown previously that sulfite oxidase deficiency can be suppressed by mutation in CTH." (PMID 36671528, 2023).
triple-negative breast carcinoma (1 paper, 2024). An invasive breast carcinoma which is negative for expression of estrogen receptor (ER), progesterone receptor (PR), and human epidermal growth factor receptor 2 (HER2). "Notably, CTH has been implicated in triple-negative breast cancer (TNBC)." (PMID 38388661, 2024).
ulcer (1 paper, 2020). "However, in chronic experimental gastric ulcer study, the daily treatment with CO donor throughout 9 days period, accelerated ulcer healing and upregulated mRNA expression for CTH and CBS increasing H2S production at the gastric mucosa of ulcer margin." (PMID 32183095, 2020).
Werner syndrome (1 paper, 2017). "CTH was decreased in fibroblasts from patients with Werner syndrome, leading to an excess activation of the mammalian target of rapamycin (mTOR)." (PMID 28275217, 2017).
tumor (41 papers, 2014 to 2026). "CTH-expressing T cells reduced glycine, serine, and proline concentrations in the tumor interstitial fluid and had a superior control of tumor growth." (PMID 40438593, 2025). "The results showed that in BC, the CTH‐H2S axis is positively correlated with the presence of an anti‐tumor phenotype in TAMs." (PMID 39755930, 2025). "Experimental validation of a key model gene (CTH) in both in vitro and in vivo systems confirmed its functional role in tumor progression." (PMID 41153607, 2025). "To evaluate the in vivo relevance of CTH, we established a xenograft tumor model by subcutaneously injecting OCI-LY7 cells transduced with either shCTH or shNT into immunodeficient mice." (PMID 41153607, 2025). "Several studies have reported that T cells overexpressing either Slc7a11 or cystathionine-gamma-lyase, the key enzyme converting methionine to cysteine, exhibit enhanced tumor suppression." (PMID 38360744, 2024). "In vivo, the genetic ablation of CTH in the host led to a significant reduction of the tumor volume and the protumorigenic and stemness transcription factor sex determining region Y-box 2 (SOX2)." (PMID 37300955, 2023). "and Principal Results: An established allogenic immunocompetent in vivo GBM model was used in C57BL/6J WT and CTH KO mice where the tumor volume and tumor microvessel density were blindly measured by stereological analysis." (PMID 37300955, 2023). "The % of tumor area and tumor volume (mm3) was analyzed by blinded stereology in all the operated WT and CTH KO mice and showed substantially smaller tumors in the CTH KO mice both in terms of % tumor area and tumor volume." (PMID 37300955, 2023). "Our results indicate similar levels of tumor microvascular density between the WT and the CTH KO mice." (PMID 37300955, 2023). "The % of tumor area and the volume was also calculated by blinded stereology solely on the WT and CTH KO that developed tumors and we reached similar statistical conclusions indicating a significant reduction of the % tumor area and tumor volume in the CTH KO." (PMID 37300955, 2023). "Previous reports showed that CTH contributed to cancer cell survival against anti-tumor therapy via enhancing antioxidant activities of the cell." (PMID 35046465, 2022). "The results showed that the expression of FGA, OTC, and CTH in the tumor tissues of patients with CCA is significantly lower than that in normal tissues, but that the expression of MMP11 is significantly higher than that in normal tissues." (PMID 36300097, 2022). "CBS silencing and pharmacological inhibition of CTH in cancer cells, the major H2S producers, reduce tumor angiogenesis." (PMID 35681715, 2022). "We found that tumor-infiltrating T cells had the highest expression of glutaminase, ribosomal protein 37, and cystathionine gamma-lyase in NSCLC, highlighting the metabolic flexibility of this cell type." (PMID 35087143, 2022). "Microvascular invasion, poor tumor differentiation, and higher TNM stage were positively associated with the depletion of CTH." (PMID 33522955, 2021). "This cell line has relatively low CTH expression among 25 HCC tumor cell lines, which is consistent with the discovery of reprogrammed sulfur metabolism in HCC tissues." (PMID 33101029, 2020). "To examine the expression of CTH during PC progression, we evaluated CTH expression in PC specimens with defined stages and grades using immunohistochemistry and a tumor TNM staging system for grouping." (PMID 31468690, 2019). "Overall, our data suggest that CTH is capable of promoting tumor growth, as well as lymph node and bone metastasis in certain PC lines such as PC3." (PMID 31468690, 2019). "Our data suggested that CTH/H2S signaling was important for tumor angiogenesis and lymphangiogenesis." (PMID 31468690, 2019). "In the CTH knockdown group, both tumor weight and tumor size decreased substantially to about 50% of those found in the shCon group." (PMID 31468690, 2019).